HOXB13 (homeobox B13)
Diseases named in the same sentence as HOXB13 in open-access papers (continued):
Sharing a sentence is not in itself a finding about the gene and the disease.
prostate carcinoma (continued). "It suppressed prostate cancer progress via sponging miR‐17‐5p and increasing HOXB13 expression." (PMID 35274492, 2022). "In addition, the alterations of gene expression are also considered to be related to the development of prostate cancer, such as HOXB13, BRCA1, BRCA2, as well as our protagonists HSP90 and HSP70." (PMID 36294924, 2022). "Also, the HOXA11-AS combination with HOXB13 manipulates the level of bone-specific metastasis-related genes of prostate cancer." (PMID 35903338, 2022). "HOXB13 is not included in many of these studies but is associated with prostate cancer in European populations." (PMID 35732815, 2022). "However, this mutation is thought to potentially weaken the interaction of HOXB13 with its MEIS cofactor, and the HOXB13/MEIS interaction in turn has been shown to reduce prostate cancer metastasis by blocking the expression of specific proteoglycans." (PMID 35080776, 2022). "By doing so, we may find new ways to reconcile seemingly opposing findings regarding the role of HOXB13 in prostate cancer." (PMID 36212399, 2022). "On the other hand, HOXB13 transcripts are downregulated in mCRPC relative to primary prostate cancer, which suggests that its involvement in modifying the AR cistrome may be more relevant to early stages of the disease." (PMID 36212399, 2022). "We identified P/LP variants in a number of DDR genes and HOXB13, some of which have not been previously identified in prostate cancer, further emphasizing the importance of these genes in carcinogenesis." (PMID 36446039, 2022). "However, to better dissect the role of HOXB13 in prostate cancer, both the clinical stage of the disease and the history of AR-targeting therapies should be considered when evaluating clinical data." (PMID 36212399, 2022). "HOXA11-AS-regulated CCL2/CCR2 may modulate the expression of HOXB13/HOXA11-AS-regulated integrins in prostate cancer; however, this interaction requires further investigation in future studies." (PMID 33514011, 2021). "The NCCN does not specify management of HOXB13 pathogenic variant carriers but acknowledges it as a variant associated to an increased risk for prostate cancer." (PMID 34711244, 2021). "To further confirm our results, we investigated known AR signaling genes more closely and as well as genes encoding for proteins that are most commonly associated with AR biology in prostate cancer (FOXA1, AR, and HOXB13), and found them virtually identical across all samples." (PMID 33576154, 2021). "Additionally, microarray-based transcriptome analyses revealed the progressive upregulation of HOXB13 in PCa cells, and HOXB13 is considered a marker for prostatic cancer origins, to distinguish metastatic PCa from other cancers." (PMID 33531604, 2021). "Linkage disequilibrium patterns suggested the presence of novel prostate cancer risk signals, independent of HOXB13 G84E." (PMID 34059701, 2021). "HOXB13 seems to be an oncogene for ovarian and prostate cancer." (PMID 34722321, 2021). "Germline mutations in the transcription factor HOXB13 and DNA damage repair genes such as BRCA1, BRCA2, CHEK2, as well as the mismatch repair (MMR) genes MSH6 and PMS2, have been shown to increase the risk of prostate cancer, the most common cancer among men." (PMID 32197306, 2020). "Interestingly, a significant fraction of breast cancer risk SNPs have been found to alter the affinity of chromatin for pioneer factor FOXA1 with which HOXB13 interacts in prostate cancer cells." (PMID 32546843, 2020).
prostate carcinoma (continued). "HOXB13 acts as a transcription factor and, together with the androgen receptor (AR) and FOXA1, regulates expression of the RFX6 gene which encodes a driver of prostate cancer progression." (PMID 32546843, 2020). "A study in over 6000 patients, found that HOXB13 gene mutations were significantly more likely in individuals with prostate cancer compared to those without (OR 20.1; 95% CI, 3.5–803.3)." (PMID 32197306, 2020). "Our study, by contrast with prostate cancer, shows that HOXB13 is not a material breast cancer susceptibility gene." (PMID 32546843, 2020). "In addition, we showed colocalization of HOXC4 and HOXC6 at HOXB13 sites that are also bound by FOXA1 and AR, which have been previously linked to regulation of prostate cancer cell proliferation." (PMID 32012197, 2020). "While HOXB13 regulates Androgen Receptor (AR) functions in a context dependent manner, its critical effectors in prostate cancer (PC) metastasis remain largely unknown." (PMID 31273254, 2019). "Familial clustering of prostate cancers was reported and ~5% of cases of prostate cancer could be directly related to highly penetrant mutations at the level of BRCA1, BRCA2, and HOXB13." (PMID 31366128, 2019). "We have previously identified AURKB as a HOXB13 transcriptional target in prostate cancer." (PMID 31273254, 2019). "Interestingly, AR-V7 and HOXB13 are coexpressed in the same tissues and circulating tumor cells in prostate cancer patients." (PMID 31366128, 2019). "Homeobox B13 (HOXB13, ENSG00000159184) is a susceptibility gene for prostate cancer." (PMID 28970820, 2017). "Given that HOXB13 is known to interact with AR signaling and plays an important role in prostate development, the HOXB13 variation may also disrupt the AR pathway and promote prostate cancer initiation and progression." (PMID 28598379, 2017). "Interestingly, the expression of HOXB13 was also found as an independent prognostic marker in primary prostate cancer and to correlate with AR expression." (PMID 28555048, 2017). "By further integrating with ChIP-seq data, our study is able to refine these candidate SNPs that are overlapped with active histone modifications, and transcription factor binding including FOXA1 and HOXB13, the critical transcription factors during prostate cancer development." (PMID 26979803, 2016). "At present it is uncertain if prostate cancer due to germline mutations in HOXB13 is more or less aggressive than prostate cancer not due to such mutations and such clinical data will determine how such patients should be screened and managed." (PMID 28031937, 2016). "HOXB13 has been reported as overexpressed in castration- resistant prostate cancers." (PMID 28005952, 2016). "By evaluating germline mutations of the HOXB13 gene in 2,433 prostate cancer families from the ICPCG, this study confirmed the observation that the G84E mutation is significantly associated with prostate cancer in subjects of European descent with family history of the disease." (PMID 23064873, 2013). "Recently, we investigated the functions of polycomb group (PcG) proteins and their epigenetic actions in silencing of HOXB13 in prostate cancer cells, and found that there was a crosstalk between histone acetylation and members of PcG proteins on repressing the HOXB13 expression." (PMID 22808286, 2012). "To further clarify whether EZH2 and BMI1 participated in HOXB13 transcriptional repression in DU145 prostate cancer cells, we constructed EZH2 siRNA and BMI1 siRNA plasmids and transfected them into DU145 cells, respectively." (PMID 22808286, 2012). "To clarify whether HOXB13 plays a role in ATRA-induced growth arrest in prostate cancer cells, we first tested the relative cell survival rate upon the treatment of ATRA." (PMID 22808286, 2012). "Also, we previously reported that YY1 and the histone deacetylase 4 (HDAC4) affected prostate cancer cell growth by repressing HOXB13 transcription through histone modification." (PMID 22808286, 2012).
prostate carcinoma (continued). "However, the role of the HOXB13 in androgen-independent growth of prostate cancer cells remains unexplained." (PMID 20504375, 2010). "Transgenic mice containing homozygous mutations of the HOXB13 gene, in contrast, do not appear to be predisposed to prostate cancer development." (PMID 15583692, 2005). "Our results show that HOXB13 transcripts could be detected in all specimens of prostate cancer and in most cases at levels comparable or above those found in normal prostate." (PMID 15583692, 2005). "A ChIP-seq of (acK13)-HOXB13, HOXB13, and H3K27ac signals analysis in tumour and normal samples has revealed that (acK13)-HOXB13 occupies an SE targeting lineage (AR, HOXB13), CRPC promoting (ACK1), prostate cancer diagnostic (FOLH1, SPON2), and angiogenesis-related (VEGFA) genes in cancer samples." (PMID 38542080, 2024). "Notably, we also found a significant downregulation of HOXB13, an androgen co-stimulatory factor, the absence of which leads to lipid accumulation in prostate cancer cells, which increases cell motility and causes metastasis in xenograft tumors." (PMID 38254880, 2024). "HOXB13, a member of the homeobox family, codes for a protein with an important role in urogenital development and which retains high levels of prostate expression even in adults, although the molecular mechanism by which HOXB13 promotes prostate cancer development remains unknown." (PMID 37239385, 2023). "Therefore, we speculate that the induction of PSMA that we observe in prostate cancer cells upon Duta treatment might be HOXB13 related and AR independent." (PMID 37569712, 2023). "Another study comprising 9,012 men diagnosed with different cancers showed a rate of 0.54% (49/9012) of HOXB13 G84E mutation carriers, of whom 1.4% (19/1362) were positive for prostate cancer compared with 0.4%(23/5,898) of HOXB13 G84E mutation carriers without prostate cancer (p < 0.05)." (PMID 35785170, 2022). "Moreover, a study conducted in unrelated subjects of European descent revealed, HOXB13 G84E mutation was detected in 1.4% (72/5083) and 0.07% (1/1401) of participants with- and without prostate cancer, respectively (P<0.05)." (PMID 35785170, 2022). "However, even when not mutated, HOXB13 transcript levels are higher in clinical samples of localized disease compared to adjacent normal tissue, suggesting that HOXB13 overexpression may be a feature of primary prostate cancer." (PMID 36212399, 2022). "Study patients who did not carry the HOXB13 variant but carried the SKAP1 variant had 3.6-fold elevated risk for prostate cancer, not baseline risk as might otherwise be interpreted by a negative clinical HOXB13 test." (PMID 34059701, 2021). "Moreover, a man who had inherited both HOXB13 G84E and the SKAP1 sentinel could have considerably greater risk of early onset, aggressive prostate cancer than might be appreciated by knowledge of G84E carriage alone." (PMID 34059701, 2021). "Utilizing positional cloning with linkage analysis successfully linked hereditary prostate cancer gene 1 (HPC1) at 1q24-25, HPCX (Hereditary Prostate Cancer gene X) at Xq27-28, linkage at 8p22-23, HPC20 (Hereditary Prostate Cancer gene 20) at 20q13, HOXB13 (Homeobox B13) and others." (PMID 34820334, 2021). "In Sweden, the Regional Cancer Committee advises against routinely testing for this HOXB13 variant in families, since individuals not carrying the variant cannot be dismissed from clinical screening for prostate cancer, and the consequences of testing family members are not yet known." (PMID 34711244, 2021). "An unbiased analysis of DNA methylation and gene expression data using a large set of tumors from TCGA identified HOXB13, HOXC4, HOXC5, and HOXC6 in the set of the top 10 transcription factors whose expression is linked to the creation of newly active distal regulatory elements in prostate cancers." (PMID 30866492, 2019).
prostate carcinoma (continued). "However, a recent study provided evidence that HOXB13 could represent an important mediator of AR-V7 in prostate cancer cells." (PMID 31366128, 2019). "Given the tight association of PTEN loss with adverse outcomes in prostate cancer, this finding would seem to suggest that HOXB13 G84E carriers may have more indolent disease compared to non-carriers." (PMID 28186998, 2017). "In addition to prostate cancer, the HOXB13 gene may be involved in the development of ovarian cancer, bladder cancer progression, oral squamous cell carcinoma aggressiveness, and breast cancer aggressiveness and tamoxifen treatment response." (PMID 25629170, 2015). "In addition to our findings for prostate cancer, the HOXB13 G84E mutation was associated with non-prostate cancers overall, allowing for correlation among the various cancer types (LD-adjusted OR = 1.63, 95% CI = 1.22–2.29, p = 0.00058)." (PMID 25629170, 2015). "In prostate cancer cell lines, several AR regulators have been identified, including GATA2, HOXB13, FOXA1, and TFAP2C." (PMID 41596366, 2026). "CRPC samples exhibited significantly higher HoxB13 staining than ADPC or normal prostate samples, suggesting that HoxB13 expression increases during prostate cancer progression to the lethal phase." (PMID 40349174, 2025). "In prostate cancer liver metastasis models driven by HoxB13, repeated systemic SCORT‐Cas13d‐gHoxB13 treatment significantly decreases HoxB13 expression, reduces metastasis, and extends mouse survival." (PMID 40349174, 2025). "We replicated these findings in a second cohort of 48 primary prostate cancer tumors profiled via ChIP-seq for H3K27ac, H3K4me2, H3K4me3, FOXA1, and HOXB13." (PMID 39945744, 2025). "GIGGLE analysis revealed a significant overlap between H3K27ac lost sites and the cistromes of key transcriptional and epigenetic regulators of prostate cancer, including AR, FOXA1 and HOXB13, supporting their functional relevance." (PMID 39117800, 2024). "While it was initially thought that PSMA expression is controlled largely by AR, more recent findings have identified HOXB13 as an upstream regulator for PSMA expression in both AR+ and AR- prostate cancer lesions." (PMID 39273701, 2024). "We have demonstrated HOXB13 as a target gene of SLC12A5-YTHDC1 complex, supporting the oncogenic role of SLC12A5 in prostate cancer." (PMID 36609444, 2023). "We selected several oncogenes that promote the malignant transformation of prostate cancer, especially several transcription factors such as BRN2 and HOXB13." (PMID 36609444, 2023). "Here we report that SLC12A5 functions as an oncogene to promote tumor progression and castration resistance of prostate cancer through the N6-methyladenosine (m6A) reader YTHDC1 and the transcription factor HOXB13." (PMID 36609444, 2023). "Several pioneer transcription factors are recognized as drivers of prostate cancer initiation and progression, including the forkhead box A1 (FOXA1) transcription factor, the homeobox protein HOXB13, and the GATA binding protein 2 (GATA2)." (PMID 36212399, 2022). "For example, in prostate cancer, HOXC8 acts as an oncogene, while HOXB13 acts as a tumor suppressor gene." (PMID 36192513, 2022). "De novo motif and binding analysis for the regulation of transcription (BART) analyses of AU-15330-compacted sites identified DNA-binding elements for major oncogenic transcription factors in prostate cancer, including AR, FOXA1, HOXB13 and ERG." (PMID 34937944, 2022). "In the following review, we will discuss the transcription factors FOXA1, HOXB13, GATA2, ERG, and MYC as they relate to the AR cistrome and its transcriptional output during prostate cancer evolution." (PMID 36212399, 2022). "In promoting proliferation in ART, CREB5 exhibited a strong degree of interaction with known AR transcription machinery, including FOXA1, HOXB13, and GRHL2, as well as novel prostate cancer regulators TBX3 and NFIC." (PMID 35550030, 2022).
prostate carcinoma (continued). "HOXB13, a member of the homeobox (HOX) gene family, is a homeodomain transcription factor that is involved in prostate cancer development." (PMID 33947030, 2021). "The HOXB13/HOXA11-AS axis also regulated integrin subunits (ITGAV and ITGB1) specific to prostate cancer bone metastasis." (PMID 33514011, 2021). "Our studies demonstrate that HOXC4 and HOXC6 co-localize with HOXB13, FOXA1 and AR, three transcription factors previously shown to contribute to the development of prostate cancer." (PMID 32012197, 2020). "Interactions between MEIS1 and HOXB13 were detectable in normal PrECs; such interactions decreased with lower MEIS expression in prostate cancer cells." (PMID 32553107, 2020). "In addition, HoxB13, which is identified as a target gene of SFMBT2 transcriptional repressor, may contribute to NF-κB-mediated prostate cancer metastasis because over-expression of HoxB13 leads to reduced expression of IκBα and enhanced the nuclear translocation of NF-κB p65 in LNCaP cells." (PMID 32971847, 2020). "We observe that these six CREs can be bound by multiple TFs in prostate cancer cells, including FOXA1, AR, and HOXB13." (PMID 31974375, 2020). "In an elegant recent study, T2E was found to physically interact with HOXB13 and FOXA1, thereby inducing T2E-specific cis-regulatory landscape in T2E-positive prostate cancer compared with non-T2E cases." (PMID 31013831, 2019). "In prostate cancer cells, the BET bromodomain protein family member, BRD4, epigenetically regulates HOXB13 expression." (PMID 31273254, 2019). "To further test the TF enrichment, we carried out ChIP assays, followed by quantitative PCR and confirmed the chromatin binding of prostate cancer master regulators AR, FOXA1, and HOXB13 at the SNP site." (PMID 29789573, 2018). "Prostein and PSA correctly detected 82% of cases, HOXB13 and PSA labeled 94.2% of cases correctly, AR and PSA detected 100% of cases, and ERG and PSA recognized 88% of prostate cancer metastases." (PMID 28555048, 2017). "The list of 10 genes again included the well-established prostate cancer markers KLK2, KLK3 (PSA), FOLH1 (PSMA), PSGR (OR51E2), STEAP2, NKX3.1 and Prostein), and also included NCAM2, SPON2 and HOXB13." (PMID 15583692, 2005). "Thus, HOXB13 and TBX3 can be considered together as potential targets for the development of specific inhibitors that suppress prostate cancer cell growth." (PMID 41164275, 2025). "In addition to common essential genes, genes with known relevance to prostate carcinoma pathobiology, including AR, FOXA1, HOXB13, GATA2, SPOP, and AKT, were depleted." (PMID 40956611, 2025). "Contributions of molecular diagnostics and next-generation sequencing being a new era of prostate cancer testing for Novel genetic biomarkers, like BRCA1/2, HOXB13, ATM, CHEK2, and DNA mismatch repair (MMR) genes, provide insight into inherited risk, disease progression, and targeted therapies." (PMID 40433050, 2025). "By contrast, GO analysis of the genes upregulated in the BPH-PCa group while downregulated in men with symptomatic BPH were several transcription factors related to prostate cancer, such as NKX3-1 and members of the HOX family like HOXB13, HOXB7, HOXD4, HOXC10 and HOXC8." (PMID 38201640, 2024). "Furthermore, having a family member with breast cancer can increase the chance of developing prostate cancer due to their genetic makeup (e.g., BRCA1, BRCA2, HOXB13, CHEK2, HOXB13 and ATM)." (PMID 37893854, 2023). "One study found that transcription factor homeobox B13 (HOXB13), identified as an upstream regulator of HOXA11-AS, could positively regulate the expression of HOXA11-AS in prostate cancer." (PMID 35903338, 2022). "In an in vitro experiment, HOXB13 and MEIS1 interact to regulate the proliferation and apoptosis of multiple prostate cancer cell lines (DU145, E006AAT, PC3, CWR22RV1, LNCaP, LNCaP C4-2, and VCap), which is believed to regulate the development of prostate cancer." (PMID 36294924, 2022).